BCL2 (BCL2 apoptosis regulator)
Diseases named in the same sentence as BCL2 in open-access papers (continued):
Sharing a sentence is not in itself a finding about the gene and the disease.
tumor (continued). "Bcl-2 and Bax are classic molecules that influence cellular proliferation and apoptosis and play important roles in tumor development." (PMID 40351419, 2025). "Mechanistic studies indicated that 6-HMDN induced tumor cell apoptosis by modulating the Bcl-2/Bax protein balance and activating the caspase cascade." (PMID 40563454, 2025). "This inflammatory milieu not only supports tumor cell proliferation and invasion but also promotes tumor cell survival by activating anti-apoptotic genes (such as Bcl-2 and IAPs)." (PMID 40563359, 2025). "The BIM deletion polymorphism involves a 2903-bp deletion that results in the loss of the pro-apoptotic BCL2 homology domain 3 (BH3) in BIM isoforms, thereby inhibiting tumor cell apoptosis." (PMID 41487577, 2025). "It is important to clarify that serum Bcl-2 refers to the presence of Bcl-2 protein in the bloodstream, often released from dying or damaged cells, including tumor cells." (PMID 40841912, 2025). "Venetoclax is a selective Bcl-2 inhibitor that promotes apoptosis of tumor cells by inhibiting the Bcl-2 protein." (PMID 40666527, 2025). "Another case is BNIP3, which can competitively bind Bcl-2 and release Beclin1 to promote autophagy and protect tumor cells." (PMID 40761374, 2025). "Maslinic acid and hederagenin can induce the apoptosis of other tumor cells by downregulating the expression of Bcl-2 and upregulating that of Bax." (PMID 40076586, 2025). "A reverse paracrine mechanism has also been identified in hematologic malignancies, where stromal cells secrete Hh ligands that enhance tumor cell survival by upregulating Bcl-2, inhibiting apoptosis." (PMID 40003637, 2025). "At the same time, the impacts of DAPs on tumor growth in tumor-bearing mice as well as the expression levels of Ki67, Bax, Bcl-2, and caspase-3 proteins were investigated to clarify the inhibitory effect on A549 cells." (PMID 39796398, 2025). "Bcl-2 protein expression is known to be upregulated in patients with iTCL-GI, potentially conferring anti-apoptotic properties to tumor cells and thereby contributing to their prolonged survival." (PMID 40666527, 2025). "Given that BCL2 supports the survival of hematopoietic tumor cells, these findings suggest that venetoclax directly targets EBV-infected cells in sCAEBV." (PMID 40425709, 2025). "In a mouse 4T1 flank tumor study, MnTnHex-2-PyP5+/Asc/radiation downregulated BCL2 along with NF-кB and other prosurvival and metastatic proteins." (PMID 40900760, 2025). "Research indicates that METTL3 facilitates tumor progression by regulating genes such as Bcl-2, EPPK1, and ACIN1." (PMID 40572597, 2025). "This study elucidates the mechanism underlying Nrf2-driven tumor progression in ATC, identifying BCL-2 and SLC7A11 as key transcriptional mediators of anoikis resistance." (PMID 41212415, 2025). "DQA is an inhibitor of apoptotic proteins that can directly inhibit the activity of caspases, regulate apoptosis through multiple pathways, and promote the degradation of Bcl-2 as an E3 ligase, thereby exerting anti-tumor effects." (PMID 41246345, 2025). "In cancer stem cells (CSCs) marked as CD44+/CD133+, restoring miR-34 reduced the CSC population by 87% by suppressing their growth and decreased tumor formation by lowering Bcl-2 and Notch1/2 levels." (PMID 40699746, 2025). "Transfection of sh-circ-MBOAT2#1 significantly increased the apoptosis rate and Bax level and reduced Bcl-2 level in tumor cells." (PMID 40369698, 2025). "This section critically examines Bcl-2’s specific involvement in various cancers, emphasizing its influence on tumor survival, therapeutic resistance, and its potential as a therapeutic target." (PMID 40841912, 2025). "It is also well known that NF-κB has direct connections to the regulation of Bcl-2 and Cyclin D1 expression to desensitize tumor cells, including in GBM." (PMID 40564997, 2025).
tumor (continued). "In contrast, anti‐apoptotic Bcl‐2, and proliferation‐associated proteins Ki67 and PCNA, were significantly downregulated, suggesting that the treatment effectively inhibits tumor growth and induces apoptosis." (PMID 40830080, 2025). "What's more, PG regulates redox balance, slows tumor growth, and significantly increases the sensitivity of tumor cells to radiation when combined with gamma rays by interfering with the Bcl‐2/caspase‐3 and PPAR‐γ signaling pathways." (PMID 41287826, 2025). "Venetoclax can selectively target to inhibit BCL2, restore the apoptotic process, replace pro-apoptotic proteins, and impart cytotoxicity on BCL2-overexpressed tumor cells, ultimately contributing to the killing of tumor cells." (PMID 39735667, 2025). "By silencing genes responsible for chemoresistance, such as MDR1 or Bcl-2, gene editing can sensitize tumor cells to chemotherapy, enhancing drug efficacy." (PMID 40573996, 2025). "Tumor cells often develop tolerance to low concentrations of NO by upregulating anti-apoptotic proteins such as Bcl-2, whereas immune cells like T lymphocytes tend to be more susceptible to NO-induced apoptosis." (PMID 41036604, 2025). "Isovitexin reduces the levels of p-PI3K, p-Akt, p-mTOR, and Bcl-2 in tumor tissues, thereby inhibiting the migration, invasion, and EMT of cancer cells." (PMID 40949141, 2025). "Its overexpression increases survival genes (including Bcl-2 and Bcl-xL) and encourages the growth of tumor cells." (PMID 40670469, 2025). "Upon activation of the IL-6/JAK/STAT3 signaling pathway, the expression of genes such as Cyclin D1 and Bcl-2 is upregulated, promoting tumor cell cycle progression and inhibiting apoptosis, thereby enhancing tumor cell proliferation and survival." (PMID 40909292, 2025). "BH3 mimetics, such as venetoclax, are designed to inhibit Bcl-2 and restore apoptotic potential in tumor cells, with promising results in hematological malignancies." (PMID 40699859, 2025). "Tumor cells upregulate BCL-2, BCL-XL, and MCL-1, allowing them to evade apoptosis even in the presence of DNA damage or therapy." (PMID 41020820, 2025). "Among them, miR-129 (hsa-miR-129-2-3p) has been identified as a tumor suppressor implicated in the regulation of oncogenic pathways, including HMGB1, BCL2, and thymidylate synthase." (PMID 41157276, 2025). "The formulation significantly curtailed tumor growth, lowered ascitic volume, and enhanced mean survival time via coordinated regulation of apoptotic (Bax, Bcl-2, Caspase-3) and angiogenic (VEGF) pathways." (PMID 41301523, 2025). "In luminal A (HR+ and HER2-) and triple-negative subtypes, the expression of BCL-2 in tumor cells was significantly correlated with factors such as tumor size and tumor grade." (PMID 40104496, 2025). "•In a retrospective HNSCC cohort, pre-treatment BCL2-positive tumors have shorter progression-free and overall survival and higher tumor recurrence rates when BCL2 status is analyzed by immunohistochemistry." (PMID 39970625, 2025). "The selected DNAzymes, DNZ-15 and DNZ-35a, effectively downregulate BCL-2 expression in human and mouse cancer models, induce apoptosis, and suppress tumor growth in vivo." (PMID 40643466, 2025). "The combined SMA (+) and Bcl-2 (+) phenotype strongly supports the diagnosis of a benign tumor of smooth muscle or myofibroblastic origin, consistent with previous literature reports." (PMID 41204504, 2025).
tumor (continued). "Further, increased expression of cleaved‐PARP1 and decreased expression level of Bcl‐2 were detected in the tumor cells exposed to Bufalin." (PMID 40908551, 2025). "When the 1097 tumor samples were compared with 114 normal tissue samples, it was shown that BAX gene had enhanced expression profile while BCL2 had lower median in tumor tissues." (PMID 41154846, 2025). "This miRNA cluster operates as a canonical tumor-suppressive axis by targeting genes associated with proliferation and EMT, such as BCL2, CCND1, and VEGFA." (PMID 41303609, 2025). "In in vivo models, MCL-1 inhibition led to complete clearance of senescent tumor cells and metastases, whereas BCL-2 inhibition with Navitoclax resulted in only partial effects." (PMID 41298369, 2025). "The standard double-color FISH tests confirmed that all tumor cells had translocations involving IGH/BCL2 and IGH/MYC, along with a BCL6 gene rearrangement." (PMID 41142614, 2025). "CREB, a downstream effector of AKT, drives anti-apoptotic genes such as BCL2 and survivin, further supporting tumor progression." (PMID 41568368, 2025). "Sertraline also sensitizes tumor cells to apoptosis, analogous to venetoclax, a Bcl‐2 inhibitor used in hematologic malignancies." (PMID 40874450, 2025). "Collectively, these mechanisms suggest that in HALs, virus-induced survival signals and oncogenic drivers, including MYC, converge to sustain tumor proliferation despite reduced BCL2 expression." (PMID 40496610, 2025). "In contrast, the co-treatment reduced the levels of Bcl-2 and pro-caspase-3 within the tumor compared to AA or VPA treatment alone." (PMID 40722968, 2025). "In contrast, the expression levels of STAT3 downstream target genes—such as VEGFA, IL-6, MMP13, Bcl2, and Twist1—remained comparable across all experimental groups, likely due to tumor excision occurring at a stage when metastasis was already underway." (PMID 40806360, 2025). "Accomplished effective Bcl-2 knockdown and increased cytotoxicity, leading to a reduction of about 50% in tumor size." (PMID 40922741, 2025). "In vivo, quadrigemine I significantly inhibited tumor growth in xenograft mice by increasing apoptosis in tumor tissues, with reduced Ki-67 and Bcl-2 expression and elevated cleaved caspase-3 levels." (PMID 40429988, 2025). "This leads to a reduction in STAT3 levels and the downregulation of Mcl-1 and Bcl-2 protein levels, thereby promoting apoptosis in tumor cells." (PMID 40142963, 2025). "For instance, in vivo and in vitro, ABT-737 and ABT-263 have shown remarkable anti-tumor activity against various hematological malignancies through inhibition of Bcl-XL, Bcl-2, and Bcl-W." (PMID 40400713, 2025). "Numerous studies have indicated that BCL2 is differentially expressed in human tumors, exerting a direct or indirect impact on the proliferation, migration, invasion, and development of tumor cells at different stages of apoptosis." (PMID 39735667, 2025). "Together, these data provide strong in vivo evidence that DNZ-15 and DNZ-35a induce tumor regression by specifically silencing BCL-2 expression at both the mRNA and protein levels." (PMID 40643466, 2025). "Through the direct suppression of BCL-2 expression, miR-125b reactivates apoptotic pathways, hence boosting tumor cell sensitivity to apoptosis." (PMID 40429954, 2025).
tumor (continued). "Accordingly, target genes of c-Myc (such as Cst1, Snai2 and Bcl2) related to tumor invasion, metastasis, and drug resistance were upregulated in Panc1 cells with NLS-TLR3 rescue, compared with other two groups." (PMID 40675966, 2025). "For example, activation of Notch1 can inhibit apoptosis by upregulating anti-apoptotic proteins (such as Bcl-2 and Survivin), thereby increasing tumor cell survival." (PMID 40621472, 2025). "In tumor cells, there is also an accumulation of calcium in mitochondria that blocks apoptosis by modifying the Bcl-2 proteins." (PMID 40305213, 2025). "Because these two processes are tightly correlated and because their crosstalk is heavily shaped by the Bcl-2:beclin-1 complex, therapeutic reprogramming aims to reshape this balance in a direction that disadvantages tumour survival." (PMID 41511337, 2025). "Compared with the normoxia group, the protein expression levels of Bax were significantly downregulated and the protein expression levels of Bcl-2 and Bcl-xL were significantly upregulated in hypoxic tumor cells." (PMID 40535800, 2025). "The genetic mutations in BCL-2 (B-cell lymphoma-2) and IDH2 (Isocitrate Dehydrogenase 2) also contribute to tumor progression." (PMID 40006565, 2025). "An imbalance in the Bax/Bcl-2 ratio, which tips the scales towards survival, can make tumor cells more resistant to a variety of cell death stimuli, including all chemotherapeutic agents, radiation, hypoxia, or growth factor deprivation." (PMID 38713435, 2025). "Based on this finding, we evaluated a combination therapy targeting BCL2, which significantly suppressed tumor growth in various xenograft models, thereby validating its therapeutic potential." (PMID 41551597, 2025). "BCL2 acts as a pivotal regulator that orchestrates the interplay between apoptosis and autophagy, involved in multiple processes of tumor cells." (PMID 41551597, 2025). "As their binding to the pro-survival BCL2 proteins are well documented, such peptides have been used as surrogates for determining the dependence of tumor cells on specific pro-survival BCL2 proteins in BH3 profiling assays." (PMID 40204951, 2025). "Akt phosphorylates pro-apoptotic proteins to enhance the anti-apoptotic function of Bcl-2/Bcl-xl, while mTOR activation accelerates protein synthesis to fuel tumor expansion." (PMID 40363681, 2025). "Akt activation inhibits apoptosis by phosphorylating pro-apoptotic proteins (e.g., BAD and BAX) and upregulating anti-apoptotic genes (e.g., Bcl-2), thereby protecting tumor cells from PCD." (PMID 40563359, 2025). "The product of this gene, the antiapoptotic protein Bcl-2, is a key regulator of tumor cell apoptosis." (PMID 41463291, 2025). "The administration of DPKCi and DPKCu polyplexes remarkably reduced the cancer cells in the tumor tissue and inhibited Bcl-2 protein expression, compared to the PBS-treated group." (PMID 39319107, 2024). "Activated Stat3 can upregulate the expression of anti-apoptotic factors, such as Bcl-2 and Bcl-xL, and downregulate the expression of pro-apoptotic factors, such as Bax, Bad, and Bid, to participate in tumor development." (PMID 39203920, 2024). "The results showed a significant reduction in the expression level of anti-apoptotic protein Bcl-2 and significant increases in the expression levels of pro-apoptotic protein Bax and Cleaved Caspase3 in mouse tumor tissues following L.p CMU-Pb-L5 intervention." (PMID 39439459, 2024). "CPP-SeNPs improved the immune system’s ability to clear tumor cells by up-regulating Bax expression while down-regulating Bcl-2 expression within solid tumors, indicating the potential activation of mitochondrial apoptosis pathway." (PMID 39767013, 2024).
tumor (continued). "Quantitative real-time PCR analysis of tumor tissues showed that the expression of Bax and the Bax/Bcl-2 ratio was upregulated after PA3264 treatment." (PMID 39169391, 2024). "BCL-2 inhibitors have transformed the treatment of hematological malignancies through direct induction of tumor cell apoptosis." (PMID 38062129, 2024). "Analysis of the mechanism using RNA sequencing demonstrate higher levels of GLI2 targets, particularly tumor growth–promoting genes, including Ccnd1, N-Myc, and Bcl2, in KrasG12D mutant cells." (PMID 38896052, 2024). "BCL2 protein is known to exert anti-apoptotic effects and its expression is usually up-regulated in tumor cells." (PMID 38671725, 2024). "The synergistic effect of TMZ and Hyp was also observed in vivo in a mouse model, as indicated by slower tumor growth, higher apoptosis rates, and reduced Bcl-2 production." (PMID 39770078, 2024). "IHC performed on the patient biopsy and CP336/CP336c revealed that Ki67 was higher in the AR-negative/BCL2-positive tumor cell population." (PMID 39286979, 2024). "Given the frequent inactivation of the mitochondrial apoptosis pathway by tumor cells, such as through overexpression of antiapoptotic Bcl-2, meriolin derivatives emerge as promising therapeutic agents for overcoming treatment resistance." (PMID 38461295, 2024). "Inhibiting Bcl-2 restores the balance between pro-apoptotic and anti-apoptotic signals within the cell, triggering apoptosis and reducing tumor survival." (PMID 39407697, 2024). "The expression of Bcl-2 and Bax expression in mice tumor tissue samples showed that Andro treatment significantly induces apoptosis compared to the untreated control group." (PMID 38797813, 2024). "Since tumor cells frequently inactivate the mitochondrial death pathway in order to acquire therapy resistance (e.g., by elevated levels of antiapoptotic Bcl-2), these meriolin derivatives display a favorable option for overcoming treatment resilience." (PMID 38461295, 2024). "The IL‐6/STAT3 pathway involves key proteins like Bcl‐2 and Bax, crucial for tumour cell apoptosis and Cyclin D1 and CDK‐4, which contribute to tumour cell proliferation." (PMID 39495702, 2024). "Sonrotoclax, a powerful and specific BCL2 inhibitor for example, is currently being studied and appears to exhibit more significant reduction of tumor development and higher cytotoxic action in different hematologic cancer cells compared to VTC." (PMID 39906657, 2024). "In this case, quercetin minimized the tumor size, along with a decrease in the expression of BCL-2 and Ki-67 in the tumor tissue." (PMID 39795061, 2024). "We used immunohistochemistry to study the expression of the pro-apoptotic protein Bax and the anti-apoptotic protein Bcl-2 in tumor tissues." (PMID 39065214, 2024). "Administration of polyplexes with pDNA significantly inhibited the increase in tumor masses, and a decrease in Bcl-2 protein was confirmed in immune-stained tumor tissues." (PMID 39319107, 2024). "In the entire 100 cases of DLBCL, 20 cases (20%) displayed MYC-positive tumor cells, and 57 cases (57%) were positive for BCL2 expression." (PMID 39038016, 2024). "In the context of tumor therapeutics, particular attention is given to the anti-apoptotic Bcl-2 proteins including Bcl-2 and Mcl-1 that are frequently overexpressed in tumors." (PMID 39372954, 2024). "Immunohistochemical staining for the inflammation marker (COX-2), Proliferation marker (Ki-67), and antiapoptotic marker (Bcl-2) showed intense staining in the tumor control group." (PMID 38469406, 2024). "It was observed that intravenous administration of a 5 mg/kg dose of α‐solanine to female BALB/c mice suppressed tumor growth by controlling the ratio of Bax and Bcl‐2, leading to the induction of apoptosis in tumor cells." (PMID 39479710, 2024).